OR6T1 (olfactory receptor family 6 subfamily T member 1)
Description:
Odorant receptor.
Synonyms: OR11-277
Tractability: Antibody: UniProt places it where antibodies can reach, with medium confidence; UniProt predicts a signal peptide or a membrane-spanning region; its Gene Ontology location is reachable by antibodies, with medium confidence.
Gene: Protein-coding gene on chromosome 11 (123,942,867 to 123,943,838, reverse strand). Ensembl gene ENSG00000181499.
Subcellular location: Cell membrane
Pathways (Reactome):
Sensory Perception: Expression and translocation of olfactory receptors
Gene Ontology:
Molecular function: olfactory receptor activity; G protein-coupled receptor activity
Biological process: detection of chemical stimulus involved in sensory perception of smell; G protein-coupled receptor signaling pathway
Cellular component: plasma membrane; membrane
Genetic constraint (gnomAD): Loss-of-function variants: 0 observed, 0.46 expected, observed/expected ratio (o/e) 0, 90% interval 0 to 1.84. That is too few expected variants to judge how well the gene tolerates losing a copy. Missense variants: 389 observed, 411.28 expected, observed/expected ratio (o/e) 0.95, 90% interval 0.87 to 1.03. Synonymous variants: 179 observed, 168.44 expected, observed/expected ratio (o/e) 1.06, 90% interval 0.94 to 1.2.
Homologues: Orthologues: dog OR6T1 (81% identical), pig OR6T1 (80% identical). Paralogues in human: OR6M1 (49% identical), OR6J1 (48% identical), OR6S1 (48% identical), OR6C75 (46% identical), OR6C76 (46% identical), OR6C70 (45% identical), OR6C74 (45% identical), OR6C3 (45% identical), OR6C65 (45% identical), OR6X1 (44% identical), OR6F1 (44% identical), OR6C2 (43% identical), and 6 more.